MYCN (MYCN proto-oncogene, bHLH transcription factor)
Diseases named in the same sentence as MYCN in open-access papers (continued):
Sharing a sentence is not in itself a finding about the gene and the disease.
neuroblastoma (continued). "The findings presented in this study, although preliminary, provide new evidence to suggest that MYCN amplification leads to antifolate sensitivity, and that methotrexate may be beneficial in a subset of patients with MYCN-amplified neuroblastoma and high SLC19A1 expression." (PMID 25860940, 2015). "Thus, increased TRPM7 expression may correlate with MYCN expression, but whether TRPM7 mRNA expression associates with disease progression in neuroblastoma patients remains to be established." (PMID 25797249, 2015). "We found that 2DG was effective in suppressing the growth of both MYCN-amplified SK-N-DZ and MYCN-non-amplified SK-N-AS neuroblastoma xenografts, which was associated with downregulation of HIF-1α, PDK1 and c-Myc, and a reduction in the number of tumor blood vessels." (PMID 26398947, 2015). "The increased expression of β-catenin in high-risk neuroblastoma, without MYCN amplification, suggests that β-catenin could play a major role in neuroblastoma." (PMID 25266063, 2015). "This study examines the ultrastructure of high-risk MYCN amplified neuroblastomas, compared with low-risk non-MYCN amplified tumours to test the hypothesis that neuroblastomas will have ultrastructural differences related to their molecular characteristics." (PMID 24679140, 2014). "The expression patterns of TRPM6 and TRPM7 in MYCN-amplified neuroblastoma cell lines and SHEP-21N cells suggests that their expression might not necessarily relate to N-Myc expression, as some MYCN-amplified cell lines had low TRPM6 expression levels (data not shown)." (PMID 25277194, 2014). "Hence, OSU-0312 was predicted to destabilize MYC and MYCN protein in neuroblastoma cells." (PMID 25017515, 2014). "Therefore, we anticipate that the positive auto-regulatory loop formed by MYCN and NCYM may be a promising target for developing novel therapeutic tools against high-risk neuroblastoma." (PMID 24391509, 2014). "A research paper in this topic shows that newly engineered PI3K inhibitors, PIK-75 and PW-12, are able to destroy the MYCN protein in mouse models of neuroblastoma and medulloblastoma, suggesting that they might be developed into useful drugs for these cancers." (PMID 26029658, 2014). "Moreover, GANT61, a GLI inhibitor, reduced the in vivo growth of high-risk neuroblastoma lacking MYCN amplification." (PMID 25134527, 2014). "However, MYCN downregulation induces apoptosis in neuroblastoma cells." (PMID 25365944, 2014). "Therefore, the feedback regulation between mTOR-S6K signaling and MYCN/NCYM may contribute to the survival of MYCN-amplified neuroblastoma cells." (PMID 24391509, 2014). "Survival analysis in the same cohort of 101 neuroblastoma tumors showed association of decreased mRNA expression levels of both RGS5 and RNF11 with poor survival (p = 4.8E-2; p = 6.4E-4), which is in line with the observed association of both genes with MYCN expression." (PMID 23308108, 2013). "Application of LLM to NB patients dataset containing the common risk factors MYCN, age at diagnosis, and INSS stage, generated rules that fit with the INRG risk assessment demonstrating the concordance of the results of LLM with previous clinical knowledge of neuroblastoma." (PMID 23815266, 2013). "Ever since MYCN was discovered to be the commonly amplified sequence in neuroblastoma (NB) tumors some 30 years ago, the mechanisms by which it contributes to NB tumorigenesis and strategies to target it have been intensively investigated." (PMID 23373009, 2013). "Therefore, amplification of MYCN expression in this neuroblastoma genetic background may repress TGF-β signaling in order to prevent cyclin D inhibition by p57cip2." (PMID 23482921, 2013).
neuroblastoma (continued). "Additionally, there is evidence that ABCB1 can also be regulated by MYCN in neuroblastoma." (PMID 22458888, 2012). "This suggests a mechanism by which MYCN may contribute to the malignant phenotype of neuroblastoma." (PMID 23181218, 2012). "More importantly, ABCC4 expression in primary neuroblastoma is strongly associated with reduced event-free survival and overall survival and multivariate analysis revealed that ABCC4 expression retained prognostic significance following adjustment for tumor stage, age, and MYCN amplification." (PMID 23267433, 2012). "Furthermore, specific suppression of MYCN expression using traditional antisense techniques or small interfering RNA molecules (siRNA) have also been shown to promote neuronal differentiation in several MYCN-amplified (MNA) neuroblastoma cell lines." (PMID 21194500, 2011). "In the present work, we show that the downregulation of miR-487b and miR-410, two miRNAs located at the 14q32.31 locus, is associated with the outcome of neuroblastoma in terms of both overall survival and relapse whether MYCN is amplified or not." (PMID 21970883, 2011). "As the tumour-suppressor function of mir-34a and -34c in MNA neuroblastoma is well documented, we selected the remaining eight experimentally validated MYCN-targeting miRNAs (mir-19a, -19b, -29a, -29b, -29c, -101, -202 and let-7e) for further functional analyses." (PMID 21654684, 2011). "A higher level of MK was correlated with MYCN amplification, low expression of TrkA, diploidy/tetraploidy, and older age, which are known prognostic factors for neuroblastoma, indicating that the elevated plasma MK concentrations is correlated with poor prognostic factors of neuroblastomas." (PMID 24281085, 2010). "Thus, MYCN causes enhanced tumorgenicity, in part, through repressing a miRNA that targets this important pro-survival gene, never previously associated with neuroblastoma pathogenesis." (PMID 20409325, 2010). "Although MYCN status is central to the risk stratification systems in all cooperative clinical trial groups, it is important to emphasise that the majority of metastatic neuroblastomas do not show amplification of this oncogene." (PMID 19401703, 2009). "However, a direct binding of MYCN to Id2 promoter has not been demonstrated and Id2 expression does not seem to be associated with MYCN amplification or expression in human neuroblastoma." (PMID 18493594, 2008). "However, the mechanisms underlying MYCN-mediated neuroblastoma progression have not been identified." (PMID 18493594, 2008). "Thus, it has been speculated that MYCN does not only mediate malignant progression in MYCN amplified tumors, but is also either involved or at least compatible with spontaneous regression in favorable neuroblastomas." (PMID 18851746, 2008). "To verify this hypothesis, we first analyzed the expression of the miRNA 17-5p-92 cluster in five neuroblastoma cell lines expressing MYCN at either low level (SH-EP and SK-N-AS) or high level due to MYCN overexpression (SH-SY-5Y) or amplification (LAN-5 and IMR32)." (PMID 18493594, 2008).
neuroblastoma (continued). "To assess whether the RA target genes identified in vitro were also modulated by RA in vivo, we treated homozygous MYCN transgenic mice with palpable abdominal neuroblastoma with 13-cis-RA (0.72–1.43 mmol 24 h−1) or solvent control, and compared target gene expression by RT–PCR." (PMID 16012519, 2005). "For example, it was shown that patients who have stage 2 neuroblastoma with MYCN amplification are at higher risk than those without it, but another study demonstrated that the presence of MYCN amplification in localised neuroblastoma does not necessarily indicate an adverse outcome." (PMID 11953858, 2002). "Exosomes, nanoscale extracellular vesicles secreted by the tumor cells, exhibit natural tropism and can be engineered to selectively target neuroblastoma-specific biomarkers such as glypican-2 (GPC2), which is highly expressed in MYCN-amplified tumors." (PMID 41750126, 2026). "In the context of MYCN−amplified neuroblastoma, Aurora−A inhibitors (e.g., MLN8054 and MLN8237) disrupt the protective Aurora−A/N−Myc complex, promoting FBXW7−mediated degradation of N−Myc and thus inhibiting tumor growth." (PMID 40370434, 2025). "MYCN is a known inhibitor of LET7, and MYCN-amplified neuroblastoma has an increased expression of LIN28." (PMID 40004600, 2025). "Extending this finding, we present evidence that in neuroblastoma, HNRNPH1 is a MYCN target, potentially explaining the higher levels of HNRNPH1 and TCF3-exon 18a transcript variants in this tumor type." (PMID 40766465, 2025). "When applied to NGP neuroblastoma cells, SK2188 degrades AURKA, induces MYCN degradation, triggers replication stress and DNA damage, and leads to apoptosis." (PMID 39802403, 2025). "In a neuroblastoma xenograft model, ARV-825 significantly down-regulates BRD4 and MYCN expression and reduces tumor growth in mice." (PMID 39802403, 2025). "In conclusion, our study has unveiled a previously unrecognized feedforward loop between MYCN and KAT2A that orchestrates an oncogenic transcriptional program in neuroblastoma." (PMID 40274766, 2025). "In addition, anti-GD2 aptamer selectively delivers into GD2+ neuroblastoma tumors the conjugates of the neuroblastoma-specific MYCN siRNA and DOX; the MYCN gene encodes the human proto-oncogene protein N-Myc (N-myc or basic helix-loop-helix protein 37 bHLHe37)." (PMID 41012445, 2025). "The MYCN‐polyamine axis is of particular significance in neuroblastoma research, since multiple genes within the polyamine pathway, including ODC1 and SLC3A2, are direct targets of MYCN." (PMID 39981745, 2025). "In neuroblastoma, TWIST1 co-occupies enhancers with MYCN and is required for MYCN–dependent proliferation." (PMID 40962798, 2025). "When MYCN is knocked down, there is a decrease in the sensitivity of MYCN and MDM2 co-amplified neuroblastoma cells to Nutlin-3 and MI-63 treatment." (PMID 39802403, 2025). "In 58 whole exome sequencing (WES) and 48 whole transcriptome sequencing (WTS) samples of MYCN non-amplified neuroblastoma (NB), recurrent mutations were observed in genes like MUC4 and RBMXL3." (PMID 39823827, 2025). "In this respect, it is noteworthy that in clinical neuroblastoma the expression of splicing and RNA processing factor genes was seen to coincide with PRMT5, E2F1 and MYCN levels, and similarly with some of the exon skipping events in the apoptotic genes." (PMID 39021294, 2025). "In neuroblastoma cells, PA2G4 and MYCN act together in a forward feedback loop, driving continued tumorigenesis." (PMID 41002386, 2025). "In this review, our primary focus will be on the roles of MYCN and MDM2 in the context of neuroblastoma." (PMID 39802403, 2025).
neuroblastoma (continued). "MYCN and MDM2 inhibition has gained attention not only in neuroblastoma but also in a spectrum of other cancer types due to their potential in targeting key oncogenic pathways." (PMID 39802403, 2025). "We further examined the SCP signature, which was highly expressed in the resistant/relapsed Th-MYCN/ALKF1178L tumors, in two human neuroblastoma cohorts (Target NBL21 and St Jude PCGP59)." (PMID 40962798, 2025). "MYCN amplification may independently predict the risk of tumor progression and confound alternative prognostic factors; while specific prognostic features in patients with high‐risk neuroblastoma without tumor MYCN amplification are unclear." (PMID 41294259, 2025). "Together, these data suggest that pathways critical for adaptive immunity are suppressed in the ADRN cell state, likely through MYCN, and are upregulated in MES-like neuroblastoma cells." (PMID 39825754, 2025). "By disrupting this complex, these compounds effectively inhibit N-Myc-dependent transcription, leading to tumor regression and prolonged survival in a mouse model of MYCN-driven neuroblastoma." (PMID 39802403, 2025). "Similarly, TFs linked to neural development including MYCN, PHOX2B, SOX10, and GATA3, drive high-risk neuroblastoma (NB)." (PMID 41228232, 2025). "Furthermore, one could consider spatial variability within tumours that involves the availability of nutrients or oxygen, as it has been reported that MYCN directly affects the cellular oxygen sensing system by interacting with HIF-1 in hypoxic neuroblastoma cells." (PMID 40993267, 2025). "In this study multiparametric MRI was used to assess tumour response to the multikinase inhibitor cabozantinib in Th-MYCN and Th-MYCN/ALKF1174L GEM models of neuroblastoma in vivo." (PMID 40359728, 2025). "Among them, MYC is the most widely expressed, covering almost all cancers, whereas MYCN and MYCL are expressed mainly in neuroblastoma and small cell lung cancer, respectively." (PMID 40732268, 2025). "Finally, we assessed whether the cellular toxicity of Cas9D10A-induced DNA damage could be attenuated in the same manner as the MYCN-amplified neuroblastoma cell lines by treating BT-474, NCI-H716, or NCI-H2170 cells with either rucaparib (PARPi) or calpastatin (CAST) in the presence of Cas9D10A." (PMID 40456709, 2025). "In this study, we expanded its application to neuroblastoma by evaluating the efficacy of DOX in the SK‐N‐DZ cell line, which is characterized by MYCN amplification." (PMID 40708972, 2025). "MYCN belongs to the MYC oncogene family, which consists of three members (MYC, MYCN, and MYCL) and was first identified in neuroblastoma." (PMID 40862719, 2025). "MYCN pro-to-oncogene (MYCN) suppresses TFPI2 and promotes tumor invasiveness, while TGFBI counteracts this by restoring TFPI2 expression in neuroblastoma." (PMID 40361374, 2025). "While all MNA-NB are classified as high-risk neuroblastomas, there is still a lack of treatment options that directly target MYCN due to an insufficient understanding of the structure of the N-Myc protein." (PMID 41244073, 2025). "Here we postulate a potential role for KAT2A in MYCN-mediated transcription and the potential for KAT2A inhibition as an anti-MYCN therapy for neuroblastoma." (PMID 40274766, 2025). "Among neuroblastoma patients, the m5C reader ALYREF forms a nuclear coactivator complex alongside MYCN, thereby prompting USP3 transcription and fostering neuroblastoma tumourigenesis." (PMID 40008496, 2025). "To further evaluate the therapeutic potential of RTA-408 against neuroblastoma in vivo, we established a cell-derived xenograft (CDX) model in mice using MYCN-amplified cells (SK-N-DZ) and non-MYCN-amplified cells (SK-N-AS)." (PMID 40493396, 2025). "In conclusion, the development of effective small molecules that inhibit both MYCN and MDM2 represents a promising new strategy for the treatment of neuroblastoma and other cancers." (PMID 39802403, 2025).
neuroblastoma (continued). "First identified in neuroblastoma (NB), the MYCN gene encodes a basic helix-loop-helix-leucine zipper transcription factor (TF) named N-Myc or MYCN that is known to be dysregulated in a number of cancers including rhabdomyosarcoma, medulloblastoma, small cell lung cancer and prostate cancer." (PMID 40274766, 2025). "ATRX gene variants may play an important role in identifying more effectively those patients who will have an increased risk of developing chronic or indolent MYCN non-amplified neuroblastoma, and should be considered for future target therapies and therapeutic approaches." (PMID 40286729, 2025). "Using inhibitors of PP2A and proteasome function and by monitoring the ubiquitination status of N-Myc, we established that silencing AF1q promotes N-Myc ubiquitination and proteasomal degradation in MYCN amplified neuroblastoma." (PMID 38413795, 2024). "Among the many transcription factors involved at different neuroblastoma differentiation stages, PHOX2B and MYCN with their transcriptional targets ALK and LIN28B, and the tumor suppressor miRNAs let-7, miR-34, and miR-204 are mainly involved." (PMID 38666930, 2024). "The expression of genes with MYCN-invaded enhancers depends on the tissue-specific transcription factor, such as TWIST1 in neuroblastoma, defining highly tumor-specific ‘MYC target gene signatures’, expanding from the canonical targets’ origined signature." (PMID 38884091, 2024). "MYCN upregulates SLC27A2 expression to enhance FAs uptake, supporting neuroblastoma survival and tumor growth." (PMID 38753091, 2024). "Conversely poor prognosis genes, potentially highly expressed because of MYCN-mediated trans-activation, are mediators of increased survival and fitness of MNA neuroblastoma cells." (PMID 39313128, 2024). "The enrichment of MYC-target gene products is of particular interest, as MYCN and C-MYC play important roles in the pathophysiology of neuroblastoma." (PMID 39767807, 2024). "Among the best-known examples are the amplifications of MYCN and MYC oncogenes in neuroblastoma and acute myeloid leukaemia (AML), respectively, in double minutes or HSR structures." (PMID 38999925, 2024). "In neuroblastoma and neuroendocrine prostate cancer, activation of the anaplastic lymphoma kinase (ALK) receptor tyrosine kinase up-regulates MYCN transcription through a STAT3-dependent mechanism." (PMID 38748789, 2024). "MYCN amplification (MNA) and disruption of tumor suppressor microRNA (TSmiR) function are key drivers of poor outcomes in neuroblastoma (NB)." (PMID 38672672, 2024). "In the current study, we report that copper chelation is an effective adjuvant strategy to potentiate anti-GD2 therapy in two preclinical immunocompetent models (Th-MYCN; NXS2) of neuroblastoma." (PMID 39668192, 2024). "Our findings demonstrate a functional relationship between MYCN and SNRPD3, which maintains the fidelity of MYCN-driven alternative splicing in the narrow range required for neuroblastoma cell growth." (PMID 38049564, 2024). "Neuroblastoma has two unique vulnerabilities—selective uptake of metaiodobenzylguanidine (MIBG) and frequent amplification of the MYCN oncogene." (PMID 38869684, 2024). "In particular, MP1 is able to inhibit protein expression of MYCN (a MYC homologue) and suppress MYCN-driven tumorigenic programs in neuroblastoma cells." (PMID 38200580, 2024). "Consistent with FN1 as a marker of mesenchymal neuroblastoma,2ALK/MYCN tumors were more mesenchymal than MYCN tumors, suggesting that ALK can bias neuroblastoma toward the mesenchymal cell state." (PMID 38451815, 2024). "To assess this possibility, we knocked down JMJD6 in neuroblastoma cell lines BE2(C) and SK-N-AS, which express MYCN and MYC, respectively, for RNA-seq analysis." (PMID 38488852, 2024).